PIGY (phosphatidylinositol glycan anchor biosynthesis class Y)
Description:
Part of the glycosylphosphatidylinositol-N-acetylglucosaminyltransferase (GPI-GnT) complex that catalyzes the transfer of N-acetylglucosamine from UDP-N-acetylglucosamine to phosphatidylinositol and participates in the first step of GPI biosynthesis. May act by regulating the catalytic subunit PIGA.
Synonyms: PIG-Y; MGC14156; HPMRS6
Tractability: Antibody: its Gene Ontology location is reachable by antibodies, with high confidence; UniProt predicts a signal peptide or a membrane-spanning region.
Gene: Protein-coding gene on chromosome 4 (88,520,998 to 88,523,776, reverse strand). Ensembl gene ENSG00000255072.
Subcellular location: Endoplasmic reticulum membrane
Pathways (Reactome):
Metabolism of proteins: Synthesis of glycosylphosphatidylinositol (GPI)
Gene Ontology:
Molecular function: phosphatidylinositol N-acetylglucosaminyltransferase activity; protein binding
Biological process: GPI anchor biosynthetic process
Cellular component: endoplasmic reticulum membrane; glycosylphosphatidylinositol-N-acetylglucosaminyltransferase (GPI-GnT) complex; plasma membrane
Genetic constraint (gnomAD): Loss-of-function variants: 3 observed, 4.35 expected, observed/expected ratio (o/e) 0.69, 90% interval 0.31 to 1.64. That is too few expected variants to judge how well the gene tolerates losing a copy. Missense variants: 78 observed, 84.37 expected, observed/expected ratio (o/e) 0.92, 90% interval 0.77 to 1.12. Synonymous variants: 33 observed, 32.98 expected, observed/expected ratio (o/e) 1, 90% interval 0.76 to 1.34.
Gene-disease validity (ClinGen):
ClinGen rates the evidence that PIGY causes each of these diseases.
hyperphosphatasia with intellectual disability syndrome 6 (autosomal recessive): Limited.
Homologues: Orthologues: rat Pigy (89% identical), tropical clawed frog pigy (89% identical), mouse Pigyl (85% identical).
Diseases named in the same sentence as PIGY in open-access papers:
PIGY is named in the same sentence as 13 diseases in open-access papers, as found by Europe PMC text mining. Sharing a sentence is not in itself a finding about the gene and the disease. The quoted sentences say what the papers report.
hyperphosphatasia (5 papers, 2017 to 2025). "Another gene involved in GPI-anchor biosynthesis, responsible for hyperCKemia is the PIGY gene (OMIM: * 610662), associated with hyperphosphatasia with impaired intellectual development syndrome 6 (OMIM: # 616809), that is, PIGY-CDG." (PMID 40718141, 2025). "Mutations in six different genes (PIGV, PIGY, PIGO, PGAP2, PIGW, and PGAP3) involved in GPI-anchor biosynthesis have been shown to cause hyperphosphatasia with mental retardation syndrome (HPMRS)." (PMID 29119105, 2017). "Recently, mutations have been identified in six genes (PIGA, PIGY, PIGO, PGAP2, PIGW and PGAP3) encoding proteins in the Glycosyl phosphatidylinositol(GPI)-anchor-synthesis pathway in individuals with hyperphosphatasia with impaired intellectual development syndrome(HPMRS)." (PMID 39687712, 2024). "To date, mutations in six genes (PIGV, PIGY, PIGO, PGAP2, PIGW, and PGAP3) have been shown to cause hyperphosphatasia with mental retardation syndrome (HPMRS) in an autosomal recessive mode of inheritance (no autosomal dominant mutations have been reported thus far)." (PMID 29119105, 2017).
congenital muscular dystrophy (1 paper, 2024). A muscular dystrophy that is characterized by diminished muscle tone (hypotonia), progressive muscle weakness and degeneration (atrophy), abnormally fixed joints, spinal rigidity, and delays in reaching motor milestones such as sitting or standing unassisted. "Causative variants were found in nine patients with congenital muscular dystrophy in the ACTA1 gene (in one patient), GFPT1 (in one patient), PIGY (in two patients), POMT1 (in one patient), MCU1 (one patient), RYR1 (one patient), and TTN (one patient)." (PMID 37989827, 2024).
Zellweger syndrome (1 paper, 2015). "Unlike patients with RCDP1 and Zellweger syndrome, patients with p.Leu46Pro substitution in PIGY do not have defective GPI lipid remodelling and are able synthesize alkyl–acyl GPI forms." (PMID 26293662, 2015).
neurological disorder (2 papers, 2019 to 2021). "PIGY upstream reading frame and orthodenticle homeobox 2 are genes associated with MIA-related neurological disorders, and presented significant under-expression in weaned relative to nursed pigs exposed to MIA, with a moderate pattern observed in non-MIA pigs." (PMID 33856433, 2021).
PIGY also shares sentences with these, for which no sentence is quoted: genetic diseases (2 papers); Intellectual disability (2); cancer (1); cataract (1); CHIME syndrome (1); Cognitive impairment (1); developmental delay (1); glycosylphosphatidylinositol deficiency (1); microcephaly (1).